MSX2 (msh homeobox 2)
Diseases named in the same sentence as MSX2 in open-access papers (continued):
Sharing a sentence is not in itself a finding about the gene and the disease.
cleft lip (4 papers, 2021 to 2025). Congenital defect in the upper lip where the maxillary prominence fails to merge with the merged medial nasal prominences. "MSX2 gene mutations have been associated with formation of different cleft lip and palate phenotypes." (PMID 33917041, 2021). "This could indicate that MSX2 might be involved with interactions between the developing oral cavity epithelium and the underlying connective tissue within the postanatal unilateral cleft lip tissue." (PMID 37733420, 2022). "The Mann–Whitney U test revealed a statistically significant difference in the number of MSX2 immunopositive epitheliocytes between the controls and the bilateral cleft lip tissue group (U=10.0, p=0.021)." (PMID 37733420, 2022). "The Mann–Whitney U test indicated a statistically significant difference in the number of MSX2 immunopositive surface epitheliocytes between the controls and the unilateral cleft lip tissue group (U=7.5, p=0.001)." (PMID 37733420, 2022). "This test indicated a statistically significant difference in the number of MSX2 immunopositive connective tissue cells between the controls and the unilateral cleft lip tissue group (U=21.0, p=0.004)." (PMID 37733420, 2022). "Median values of semiquantitative evaluation for BARX1, DLX4, FOXE1, HOXB3, and MSX2 immunoreactivity within the control tissue group, unilateral cleft lip tissue group, bilateral cleft lip tissue group, and cleft palate tissue group." (PMID 37733420, 2022). "Amongst these genes, DLX4, HOXB3, and MSX2 have been recently shown to be involved in the etiology of non-syndromic cleft lip and palate." (PMID 34834487, 2021). "Our study findings indicate that the RYK gene might be more functionally active in cleft lip tissue, possibly due to disturbed signaling pathways and tissue homeostasis characteristics, similarly to what is seen in the case of the MSX2 gene." (PMID 41226636, 2025). "This could indicate a close interaction between three factors – FOXE1, HOXB3, and MSX2 within bilateral cleft lip tissue." (PMID 37733420, 2022). "The number of MSX2 and RYK gene-signal-containing cells was significantly increased in cleft lip tissue, probably due to WNT signaling disturbances and gene activation in cleft-affected tissue." (PMID 41226636, 2025). "Immunohistochemistry (IHC) for MSX1, RYK, NFκB p65, and CCL4 proteins and chromogenic in situ hybridization (CISH) for MSX2, RYK, and PTX3 genes were used to analyze postnatal human cleft lip tissue (15 patients) and control tissue (6 patients)." (PMID 41226636, 2025). "The number of MSX2 and RYK gene-signal-containing cells was significantly increased in the cleft lip in all three evaluated tissue types (epithelium, connective tissue, and endothelium) in comparison to the control group." (PMID 41226636, 2025). "The information gathered in this study has provided additional insight about the presence and distribution of MSX1, RYK, NFκB p65, and CCL4 proteins and MSX2, RYK, and PTX3 genes in human cleft lip tissue." (PMID 41226636, 2025). "The only statistically negative correlation seen in the cleft lip patient group was identified between the MSX2 gene in connective tissue (CISH) and the CCL4 protein in the endothelium (IHC), which was not present in the control group." (PMID 41226636, 2025). "In the unilateral cleft lip tissue group the median number of MSX2 immunopositive epitheliocytes was moderate (++) and it ranged from no positive cells to numerous (+++) MSX2 positive epithelial cells." (PMID 37733420, 2022). "In the unilateral cleft lip group connective tissues, the median number of MSX2 positive structures was a few (+) and it ranged from no positive structures to moderate to numerous (++/+++)." (PMID 37733420, 2022).
cleft lip (continued). "In cleft lip patients, most statistically significant positive correlations involved the following factors: the PTX3 gene and NFκB p65 protein, then MSX1 protein-positive cells, RYK protein-positive cells, the CCL4 protein, the RYK gene, and then MSX2 gene-signal-containing cells." (PMID 41226636, 2025). "Interestingly the presence of a statistically significant negative correlation between BARX1 and MSX2 positive structures in bilateral cleft lip affected connective tissue could possibly indicate a disruption of this specific regulatory mechanisms." (PMID 37733420, 2022). "The aim of this study was to detect and compare the immunohistochemical expression of cleft candidate gene coded proteins (DLX4, MSX2, HOXB3, SHH, PAX7, SOX3, WNT3A, and FOXE1) in the non-syndromic unilateral cleft lip patient tissue and control group tissue." (PMID 33917041, 2021). "Interestingly, our study revealed that there were statistically significant negative correlations in the bilateral cleft lip tissue which were notified between BARX1 in the connective tissue and MSX2 in the connective tissue and between BARX1 in the connective tissue and DLX4 in the epithelium." (PMID 37733420, 2022).
cleidocranial dysplasia (4 papers, 2015 to 2021). "Alongside the cleidocranial dysplasia, a mutation of the MSX2 gene in humans can cause craniosynostosis and enlarged parietal foramina, whereas haploinsufficiency can lead to midline cranial defects." (PMID 34299147, 2021). "Furthermore, other genetic diseases can show a similar phenotype to that of CCD, such as parietal foramina with cleidocranial dysplasia, which results from mutations in Drosophila muscle segment homeobox gene homologue 2 (MSX2)." (PMID 34737766, 2021). "Moreover, delayed molar eruption occurs in mice with osteopetrosis induced by mutations in the genes encoding macrophage colony-stimulating factor, msh homeobox 2, and receptor activator of nuclear factor kappa-B, as well as in mice with cleidocranial dysplasia." (PMID 25830530, 2015).
colorectal cancer (4 papers, 2017 to 2024). A primary or metastatic malignant neoplasm that affects the colon or rectum. "In this study, we explored that the relative expression of the Col1a2, ITIH4, MMP7, and MSX2 are increased in the mice who induced colorectal cancer (the COL group) compared with the Normal group." (PMID 38637796, 2024). "The gene profiles (Col1a2, ITIH4, MMP7, and MSX2) were identified as critical markers in colorectal cancer." (PMID 38637796, 2024). "A recent study also describes MSX2 as playing a crucial role in the progression of colorectal cancer." (PMID 31010135, 2019). "There are few reports about the clinical implications and function of MSX2 in colorectal cancer (CRC)." (PMID 28286778, 2017). "Growing evidence has indicated that the genes of Col1a2, ITIH4, MMP7, and MSX2 profiles could be critical markers for identifying colorectal cancer." (PMID 38637796, 2024).
diabetes (4 papers, 2017 to 2023). "Studies had shown that high expression of MSX2 was associated with cardiovascular morbidity and mortality in diabetes; cardiovascular disease accounts for 80% of diabetes-related deaths." (PMID 28286778, 2017). "Although current research showed that MSX2 had oncogenic properties and correlated with the high risks of mortality in diabetes, whether it is associated with the development of CRC remains unclear." (PMID 28286778, 2017). "Our work may provide certain enlightenment for investigating the mechanism of MSX2 in the process of diabetes." (PMID 28286778, 2017). "High expression of MSX2 is related to development of diabetes." (PMID 28286778, 2017). "Our work indicated that MSX2 may be an important prognostic marker and a potential therapeutic target in CRC, which may expand our understanding of the potential mechanism of MSX2, affecting the vascular calcification in diabetes." (PMID 28286778, 2017). "Although aberrant activation of Wnt signal is one of the important causes of CRC, we hypothesize whether there is a positive feedback regulation loop between MSX2 and Wnt signaling pathways during the process of CRC and diabetes." (PMID 28286778, 2017).
Hyperglycemia (4 papers, 2017 to 2025). An increased concentration of glucose in the blood. "Elevated hyperglycaemia enhances the BMP-2/Msx2-Wnt pathway, causing some myofibroblasts to become osteogenic, while BMP-2 inhibition prevents arterial calcification." (PMID 39026232, 2024). "This transdifferentiation can be activated by hyperphosphatemia, hypercalcemia, hyperglycemia, and inflammation, and involves with various osteogenic transcription factors, including core binding factor alpha-1(CBFA1), msh homeobox 2 (MSX2), and osterix (Osx)." (PMID 33808324, 2021). "For instance, hyperglycemia and hyperphosphatemia trigger the activation of Notch1-RBP-Jk/Msx2 pathway in DN to varying degrees and at different time periods, whereas the compensatory mechanism of the body may restore their levels." (PMID 29464183, 2017).
hyperphosphatemia (4 papers, 2017 to 2025). Abnormally high level of phosphate in the blood. "Secondly, in the late stage of DN, impaired renal function causes hyperphosphatemia which stimulates Notch1-RBP-Jk signaling pathway to induce the expression of target gene Msx2, resulting in osteogenic differentiation and mineralization of VSMCs." (PMID 29464183, 2017). "In response to hyperphosphatemia, inflammation, and oxidative stress, VSMCs lose their contractile phenotype and adopt osteoblast-like features, driven by transcription factors such as Runx2, BMP2, and Msx2." (PMID 41470171, 2025).
melanoma (4 papers, 2011 to 2024). A malignant, usually aggressive tumor composed of atypical, neoplastic melanocytes. "Using TMA technology, we found that cytoplasmic expression of MSX2 was significantly associated with improved recurrence-free and overall survival of melanoma patients." (PMID 21730974, 2011). "Interestingly, BMP-induced apoptosis, similar to what has been described earlier for MSX2 over-expression in melanoma, has also been associated with a downregulation of BCL2 and Survivin." (PMID 21730974, 2011). "In addition, MSX2 was shown to be associated with good prognosis in melanoma." (PMID 21730974, 2011). "MSX2 expression has been identified as a biomarker for good prognosis in patients with malignant melanoma." (PMID 36012688, 2022). "Ectopic expression of MSX2 in melanoma cell lines led to the induction of apoptosis and inhibited cell invasion in a three-dimensional spheroid assay." (PMID 21730974, 2011). "Subsequently, the expression of MSX2 protein was assessed in tumour tissues derived from a cohort of melanoma patients." (PMID 21730974, 2011). "During in vitro characterisation studies, MSX2 was primarily located to the nucleus of melanoma cells with some cytoplasmic staining being detectable." (PMID 21730974, 2011). "Initially, the expression of MSX2 in the melanoma cell lines WM793 and 1205Lu was tested via western blot analysis." (PMID 21730974, 2011). "Ectopic expression of MSX2 resulted in the induction of apoptosis and reduced the invasive capacity of melanoma cells in three-dimensional culture." (PMID 21730974, 2011). "In an effort to explore the functionality of MSX2 in melanoma, we employed a number of in vitro functional assays using the melanoma cell line WM793 and its metastatic derivative 1205Lu." (PMID 21730974, 2011). "An evaluation of Caspase 3/7 activity and cell-cycle distribution suggested a pro-apoptotic role of MSX2 in melanoma cells." (PMID 21730974, 2011). "Overall, in vitro over-expression of MSX2 led to the induction of apoptosis and a clear reduction in melanoma cell invasiveness." (PMID 21730974, 2011). "Using a selection of two- and three-dimensional in vitro assays and tissue microarrays (TMAs), the clinical and functional relevance of MSX2 in malignant melanoma was explored." (PMID 21730974, 2011). "On the other hand, enforced expression of TAF4 promoted expression of pluripotency- associated KLF4, OCT4 and NANOG, and NC-related MSX2, PAX7, SOX10 and SNAI1, reaffirming the critical role of hTAF4-TAFH activity in the maintaining of multipotency in melanoma cells." (PMID 27499390, 2016). "Here, the functional and clinical relevance of MSX2 for malignant melanoma is explored." (PMID 21730974, 2011). "In addition, a comprehensive cohort of 218 primary melanoma samples was screened for the clinical relevance of MSX2 protein expression." (PMID 21730974, 2011). "However, SPEN interacts with MSX2, which has been previously highlighted with melanoma." (PMID 39337694, 2024). "However, both melanoma cell lines expressed low MSX2 levels compared with SKBR3." (PMID 21730974, 2011). "MSX2 may be an important regulator of melanoma cell invasion and survival." (PMID 21730974, 2011). "Epithelial cells in epithelioid melanomas are more differentiated cell types of ectodermal origin, and the downregulation of MSX1 and MSX2 expression in this type of tumor may indicate a lack of tumor suppression." (PMID 36012688, 2022).
Infertility (3 papers, 2012 to 2019). "Targeted mutation of Msx1 and Msx2 genes in female mice, which results in infertility, established that these factors suppress signaling by the morphogenic ligands, WNTS, in the uterus." (PMID 22383889, 2012). "Deletion of both Msx1 and Msx2 leads to complete infertility and aberrant expression of implantation-related genes." (PMID 31752681, 2019). "On the other hand, conditional ablation of both Msx1 and Msx2 in mouse uterus led to complete infertility due to a failure of embryo attachment to the uterine epithelium." (PMID 22383889, 2012).
ovarian carcinoma (3 papers, 2012 to 2017). A malignant neoplasm originating from the surface ovarian epithelium. "Moreover, activation of the Wnt pathway via treatment with a Wnt3a ligand or a GSK3β inhibitor resulted in strong induction of MSX2 expression in ovarian cancer cells." (PMID 27088357, 2016). "In the ovarian cancer cell lines, MSX2 expression was induced by WNT/β-catenin signaling, which had been considered as the contributor to the malignancy of ovarian cancer." (PMID 28286778, 2017). "Since the expression of MSX2 in selected ovarian carcinoma cells induced changes suggestive of EMT but MSX2 expression was not consistently correlated with EMT markers in primary tumor specimens, they speculated that the involvement of MSX2 in EMT was complex and context-dependent." (PMID 23162473, 2012).
type II diabetes (3 papers, 2018 to 2023). "TNF‐α has been demonstrated to promote arterial calcification in type II diabetes (T2DM) mouse model through enhancing Msx2‐Wnt signalling." (PMID 33369201, 2021). "Additionally, TNF-α signals stimulated by high fat diet-induced obesity and type II diabetes mellitus promotes aortic Msx2 expression, a transcription factor in the BMP signaling pathway, and enhances pro-calcific arterial Msx2-Wnt cascades." (PMID 29632866, 2018).
alopecia (2 papers, 2017 to 2025). Hair loss usually from the scalp. "This study provides new insights into hair follicle cycling dynamics and identifies Msx2 as a potential therapeutic target for promoting hair regeneration and mitigating alopecia phenotypes." (PMID 40998254, 2025). "However, the level of Sox21 remained unaltered in Msx2 null background suggesting independent mode of action of both the molecules in the development of cyclic alopecia." (PMID 28912581, 2017).
breast tumors (2 papers, 2010 to 2021). "Msx2 protein expression was then evaluated by immunohistochemistry in a tissue microarray (TMA) containing 281 invasive breast tumours." (PMID 20682066, 2010). "Having shown that Msx2 expression correlates with good prognosis in breast tumours, we proceeded to examine the role of Msx2 in vitro." (PMID 20682066, 2010). "This variation in the cellular response to Msx2 indicates that the context of Msx2 overexpression, as well as its subcellular localisation and intensity, is an important factor to consider when examining the role of Msx2 in breast tumours." (PMID 20682066, 2010). "The fact that Msx2 mRNA expression in these tumours correlates with markers of cell cycle arrest and apoptosis suggests that the apoptosis which we observed in vitro may represent a real phenomenon in breast tumours in vivo." (PMID 20682066, 2010). "Finally, to assess the functional role of Msx2 in vitro, Msx2 was ectopically expressed in a highly invasive breast tumour cell line (MDA-MB-231) and an immortalised breast cell line (MCF10a), and these cell lines were examined for changes in growth rate, cell death and cell signalling." (PMID 20682066, 2010). "The only study of Msx2 in breast tumours to date involved four invasive ductal carcinomas and found that Msx2 expression was increased in infiltrating compared to noninfiltrating cells." (PMID 20682066, 2010).
cleft palate (2 papers, 2021 to 2022). Cleft palate is a fissure type embryopathy that affects the soft and hard palate to varying degrees. "The Mann–Whitney U test revealed a statistically significant difference in the number of MSX2 immunopositive epitheliocytes between the controls and the cleft palate tissue group (U=27.5, p=0.045)." (PMID 37733420, 2022). "This test indicated a statistically significant difference in the number of MSX2 immunopositive connective tissue cells between the controls and the cleft palate tissue group (U=24.5, p=0.023)." (PMID 37733420, 2022).
Diabetic Nephropathy (2 papers, 2017 to 2021). "This study explored the changes in expression of vascular smooth muscle cell (VSMC) markers and osteogenic markers, as well as the involvement of Notch1-RBP-Jk/Msx2 pathway in a rat model of diabetic nephropathy (DN) with vascular calcification." (PMID 29464183, 2017). "Msx-2 signaling is also involved in aortic calcification in diabetic nephropathy rat model." (PMID 34502172, 2021).
gastric cancer (2 papers, 2014 to 2017). A primary or metastatic malignant neoplasm involving the stomach. "MSX2 plays an essential role in gastric cancer growth and knockdown of MSX2 of HSC60 by specific siRNAs significantly inhibited the cell growth." (PMID 28286778, 2017). "The mean methylation levels of gastric cancer tissues were higher than those of normal gastric tissues for two sites (TRIM15 and ITGAM) and lower for two sites (MSX2 and FAM38A), which were consistent with the results of the microarray analysis." (PMID 24944662, 2014). "Analysis of the results identified TRIM15, ITGAM, MSX2 and FAM38A as possible candidate sites clinically useful for the diagnosis and treatment of gastric cancer." (PMID 24944662, 2014). "qPCR results showed that the expression levels of ITGAM, MSX2 and FAM38A were upregulated in gastric cancer tissues, while the expression level of TRIM15 was downregulated (P<0.05)." (PMID 24944662, 2014). "TRIM15, ITGAM, MSX2 and FAM38A may be candidate genes for diagnosing gastric cancer." (PMID 24944662, 2014).
invasive ductal carcinoma (2 papers, 2009 to 2010). "An alternative pathway recently was demonstrated for invasive ductal carcinoma cells, in which upregulation of the homeobox transcription factor Msx2 causes activation of c-Src and a concomitant EMT." (PMID 19583841, 2009).
microphthalmia (2 papers, 2022 to 2024). Congenital or developmental anomaly in which the eyeballs are abnormally small. "For instance, apoptosis was increased by an Msx2 variant that activated the caspase-3/8 pathway and by the loss of Rbm that abolished Birc2 inhibition of anti-apoptotic pathways in mouse Msx2 models of microphthalmia." (PMID 38821055, 2024). "Mice knocked out for Msx2 exhibit cornea-lentoid adhesions and microphthalmia due to a developmental failure of the lens, a phenotype similar to human Peters anomaly." (PMID 35885921, 2022).
neuroblastoma (2 papers, 2009 to 2023). Neuroblastoma (NB) is the most common solid, extracranial childhood tumor. "Here we identified MSX2 mediated activation of the NOTCH3-pathway in T-cells reminiscent of MSX1 in neuroblastoma." (PMID 19835636, 2009).